CASTOR1 (cytosolic arginine sensor for mTORC1 subunit 1)
Description:
Functions as an intracellular arginine sensor within the amino acid-sensing branch of the TORC1 signaling pathway. As a homodimer or a heterodimer with CASTOR2, binds and inhibits the GATOR subcomplex GATOR2 and thereby mTORC1. Binding of arginine to CASTOR1 allosterically disrupts the interaction of CASTOR1-containing dimers with GATOR2 which can in turn activate mTORC1 and the TORC1 signaling pathway.
Synonyms: GATSL3
Tractability: Small molecule: a structure with a bound ligand is known. PROTAC: UniProt records ubiquitination sites on it.
Gene: Protein-coding gene on chromosome 22 (30,285,114 to 30,289,694, reverse strand). Ensembl gene ENSG00000239282.
Subcellular location: Cytoplasm, cytosol
Pathways (Reactome):
Cellular responses to stimuli: Amino acids regulate mTORC1
Gene Ontology:
Molecular function: arginine binding; identical protein binding; molecular sensor activity; protein binding; protein sequestering activity
Biological process: cellular response to amino acid starvation; cellular response to L-arginine; negative regulation of TORC1 signaling; positive regulation of TORC1 signaling
Cellular component: cytosol; GATOR2 complex
Genetic constraint (gnomAD): Loss-of-function variants: 17 observed, 28.14 expected, observed/expected ratio (o/e) 0.6, 90% interval 0.41 to 0.91. The upper end of that interval is the gene's LOEUF score, 0.91, which puts it in group 3 of 6, group 1 being the genes least tolerant of losing a copy. Missense variants: 359 observed, 430.73 expected, observed/expected ratio (o/e) 0.83, 90% interval 0.76 to 0.91. Synonymous variants: 175 observed, 182.17 expected, observed/expected ratio (o/e) 0.96, 90% interval 0.85 to 1.09.
Homologues: Orthologues: chimpanzee CASTOR1 (100% identical), pig CASTOR1 (96% identical), dog CASTOR1 (95% identical), guinea pig CASTOR1 (95% identical), rat Castor1 (92% identical), mouse Castor1 (92% identical), rabbit CASTOR1 (86% identical), tropical clawed frog castor1 (68% identical). Paralogues in human: CASTOR2 (63% identical).
Diseases named in the same sentence as CASTOR1 in open-access papers:
CASTOR1 is named in the same sentence as 8 diseases in open-access papers, as found by Europe PMC text mining. Sharing a sentence is not in itself a finding about the gene and the disease. The quoted sentences say what the papers report.
breast carcinoma (4 papers, 2021 to 2024). "Recent studies have demonstrated that ring finger protein 167 (RNF167) activates mTORC1 and promotes the occurrence of breast cancer by targeting and degrading K29-linked ubiquitinated cytosolic arginine sensor for mTORC1 subunit 1 (CASTOR1)." (PMID 39048965, 2024). "RNF167 inhibited the activity of mTORC1 by regulating the Lys-63-linked and Lys-29-linked ubiquitination of SESN2 and CASTOR1, which played a significant tumor-suppressive role in colon and breast cancer." (PMID 38304253, 2023). "In breast cancer cell lines, the protein level of CASTOR1 appears to be inversely correlated with the level of AKT activation." (PMID 33594058, 2021). "To examine the importance of AKT1-mediated phosphorylation and RNF167-mediated degradation of CASTOR1 in breast cancer cells, we overexpressed Flag-CASTOR1 WT, S14A, and S14D in HCC1569, MCF7, and T47D cells." (PMID 33594058, 2021). "Consistent with the mTORC1 activity, the proliferation and colony formation in softagar of breast cancer cells were significantly decreased by CASTOR1 WT and S14A, whereas CASTOR1 S14D had a less effect." (PMID 33594058, 2021). "Overexpression of CASTOR1 decreases cell proliferation and colony formation in softagar of breast cancer cells while genetic silencing of CASTOR1 has the opposite effect." (PMID 33594058, 2021). "In this study, we report that a low expression level of CASTOR1 is correlated with poor patient survival in numerous types of cancer including breast cancer and that CASTOR1 is a substrate of RNF167." (PMID 33594058, 2021). "Taken together, these results revealed that AKT-mediated phosphorylation and RNF167-dependent ubiquitination led to a decreased CASTOR1 protein level in breast cancer cells, resulting in enhanced mTORC1 activation, cell proliferation, and tumorigenesis." (PMID 33594058, 2021). "In vivo, high expression of RNF167 in breast tumors correlates with poor survival in human epidermal growth factor receptor 2 positive (HER2+) breast cancer while lower CASTOR1 expression was correlated with poor survival in estrogen receptor-positive (ER+) breast cancer." (PMID 35159190, 2022). "CASTOR1 S14D had much lower expression level than WT and S14A had in all the three cell lines examined, indicating that S14D also had faster turnover in breast cancer cells." (PMID 33594058, 2021). "Hence, our results have demonstrated a tumor-suppressive function of CASTOR1 in breast cancer cells, which is negated by AKT-mediated phosphorylation." (PMID 33594058, 2021). "In two pairs of ER+ and HER2+ breast cancer cell lines, we found an inverse correlation of activated AKT level with CASTOR1 protein level." (PMID 33594058, 2021). "Importantly, ectopic expression of both CASTOR1 WT and S14A significantly inhibited mTORC1, whereas CASTOR1 S14D showed a much less inhibitory effect, confirming the fine-tuning of mTORC1 signaling pathway through CASTOR1 phosphorylation and degradation in breast cancer cells." (PMID 33594058, 2021). "The phosphorylation and degradation of CASTOR1 collectively release the GATOR2 complex, activate mTORC1, and promote breast cancer progression." (PMID 33594058, 2021). "Together these results indicated that, similar to 293T cells, the CASTOR1 protein level was also regulated by AKT and RNF167 in breast cancer cells." (PMID 33594058, 2021). "Significantly, AKT and RNF167-mediated CASTOR1 degradation activates mTORC1 independent of arginine and promotes breast cancer progression." (PMID 33594058, 2021). "Furthermore, a lower CASTOR1 expression level and a higher RNF167 expression level were correlated with poor survival in ER+ and HER2+ breast cancer, respectively." (PMID 33594058, 2021).
lung adenocarcinoma (2 papers, 2023 to 2024). A carcinoma that arises from the lung and is characterized by the presence of malignant glandular epithelial cells. "The CASTOR1-dependent inhibition of mTORC1 has shown a tumor suppressor role in lung adenocarcinoma leading to lower proliferation, migration, and invasion, and when it is downregulated, it is associated with a poor prognosis." (PMID 36982390, 2023).
laryngeal carcinoma (1 paper, 2025). Carcinoma that arises from the laryngeal epithelium. "Besides, genes from molecular pathways of autophagy (ULK/ATG complex), drug efflux (ABC transporters), mitochondrial activity (V‐ATP synthase), hypoxia (HIF1A), and PI3K/mTOR (PIK3CA, CASTOR1, and DEPTOR) were upregulated in resistant laryngeal cancer cells." (PMID 40385549, 2025).
myeloma (1 paper, 2022). "Intracellular reduction of arginine can also be sensed by CASTOR1, which in turn may reduce mTORC1 activity, with potentially myeloma-relevant downstream effects, including increased autophagy or pro-survival effects via positive regulation of mTORC2 complex activity." (PMID 36172163, 2022).
cancer (6 papers, 2021 to 2025). A tumor composed of atypical neoplastic, often pleomorphic cells that invade other tissues. "Our previous works have established a tumor-suppressive role of CASTOR1, demonstrating that lower levels of CASTOR1 expression are associated with worse survival across at least 10 types of cancer." (PMID 39385301, 2024). "Given that AKT is activated by various growth factors and mutations in genes regulating AKT in cancer, CASTOR1 serves as a crucial integrator of signals from both nutrients and growth factors, thereby modulating mTORC1 activity, cell proliferation, and survival." (PMID 39385301, 2024). "Hence, it is expected that cancer cells would have evolved specific mechanisms to counter CASTOR1’s inhibitory effect on mTORC1 in nutrient-deficient tumor microenvironment." (PMID 33594058, 2021). "In other cancer types, CASTOR1 is phosphorylated at S14 (pCASTOR1) by AKT, sensitizing it to ubiquitination by the RNF167 E3 ligase and subsequent proteasome-mediated degradation." (PMID 39385301, 2024). "Since the tumor microenvironment often exhibits low arginine levels, cancer cells have evolved specific mechanisms to inhibit CASTOR1 function." (PMID 39385301, 2024). "We have previously shown a tumor suppressive role of cytosolic arginine sensor for mTORC1 subunit 1 (CASTOR1), which is targeted for degradation upon phosphorylation at S14 (pCASTOR1) in multiple types of cancer." (PMID 39385301, 2024). "This suggests that global metabolism and epigenetics can be controlled by L-arginine in cancer cells via different sensing systems, such as CASTOR1, SLC38A9, and possibly TEAD4." (PMID 36982390, 2023). "While no consistent association of CASTOR1 mutation with any types of cancer has been identified so far, we have found that a lower mRNA expression level of CASTOR1 predicts a poor prognosis in 10 types of cancer." (PMID 33594058, 2021). "Consistent with CASTOR1’s inhibitory function on mTORC1 and tumor-suppressive role, a lower CASTOR1 expression level was correlated with overall poor survival in pan-cancer analyses." (PMID 33594058, 2021). "Inhibition of CASTOR1 function is also essential for breast cancer and possibly other types of cancer by AKT mediated RNF167-targeted degradation." (PMID 34579773, 2021). "CASTOR1 is an arginine sensor that inhibits mTORC1 activation, for which this pathway is frequently dysregulated in cancers." (PMID 33594058, 2021). "These regimens are expected to deprive cancer cells of arginine, leading to CASTOR1 activation, mTORC1 suppression, and tumor regression." (PMID 33594058, 2021). "In cancer cells, anabolism dependency on L-arginine via mTORC1 has been associated with the activation of the RAGULATOR-RAG complex in the lysosomal membrane by both SLC38A9 and CASTOR1, the two intracellular sensors of L-arginine." (PMID 36982390, 2023). "Thus cancer cells at least partially utilize constitutively active AKT to inhibit CASTOR1’s function leading to constitutive mTORC1 activation." (PMID 33594058, 2021). "Whether CASTOR1 protein has a tumor-suppressive function in other types of cancer remains to be investigated." (PMID 33594058, 2021). "We examined the prognostic value of CASTOR1 mRNA expression in cancer using the TCGA database." (PMID 33594058, 2021). "Because cancer cells often encounter low levels of nutrients, an alternative mechanism might exist to regulate CASTOR1 expression." (PMID 33594058, 2021). "Pharmacological intervention of RNF167 leading to CASTOR1 activation could be considered as a potential therapeutic approach for these cancer types." (PMID 33594058, 2021). "Hence, AKT-mediated degradation of CASTOR1 could be an important mechanism of resistance to cancer therapies designed to deplete cancer cells of arginine." (PMID 33594058, 2021). "The differential regulation of mTORC1 by amino acid sensors such as Sestrin2 (leucine), CASTOR1 (arginine), and SAMTOR (methionine) underscores the complexity of nutrient sensing in cancer." (PMID 40427696, 2025).
cancer (continued). "The fact that a low mRNA expression level of CASTOR1 and a high mRNA level of RNF167 predict a poor prognosis of these cancer types suggest the existence of an additional mechanism(s) regulating their mRNA expression." (PMID 33594058, 2021). "As no specific CASTOR1 mutation associated with cancer has been described so far, how other cancer cells evade the inhibitory effect of CASTOR1 on mTORC1 in nutrient-deficient, especially AA-deficient, tumor microenvironment in other types of cancer remains unclear." (PMID 33594058, 2021). "Furthermore, KSHV dysregulates numerous metabolic sensors including mTOR, AMPK, CASTOR1 and sirtuins to maintain cellular energetic homeostasis during infection and in KSHV-induced cancers." (PMID 34579773, 2021).
tumor (6 papers, 2021 to 2024). "This is consistent with the tumor suppressive function of CASTOR1, which must be inhibited in order to achieve constitutive activation of mTORC1 for tumor cell growth." (PMID 39385301, 2024). "KSHV miRNAs targeting CASTOR1 activates mTORC1 and relieves the tumor suppressive effect of CASTOR1." (PMID 34579773, 2021). "While the constitutively phosphorylated mutant S14D has a reduced inhibitory effect, the dead phosphorylated mutant inhibits tumor growth even more effective than the WT CASTOR1, possibly due to its dominant-negative effect." (PMID 33594058, 2021). "Ectopic expression of CASTOR1 WT and S14A significantly inhibited tumor growth in vivo, whereas S14D had a relatively less effect." (PMID 33594058, 2021). "Consistently, silencing of CASTOR1 in T47D cells promoted tumor growth in vivo and shortened the overall survival compared to a scrambled control group." (PMID 33594058, 2021). "In a mouse tumor model, overexpression of WT CASTOR1 inhibits tumor growth and extends animal survival rate." (PMID 33594058, 2021). "The phosphomimetic variant of CASTOR1, which causes lower CASTOR1 protein abundance, did not inhibit mTORC1 activation, tumor growth, or cell proliferation." (PMID 35159190, 2022). "CASTOR1 is tumor suppressive in KSHV-induced cellular transformation and lung adenocarcinoma." (PMID 33594058, 2021).
CASTOR1 also shares sentences with these, for which no sentence is quoted: infection (1 paper); mastitis (1).